LLGL1 (LLGL scribble cell polarity complex component 1)
Description:
Cortical cytoskeleton protein found in a complex involved in maintaining cell polarity and epithelial integrity. Involved in the regulation of mitotic spindle orientation, proliferation, differentiation and tissue organization of neuroepithelial cells. Involved in axonogenesis through RAB10 activation thereby regulating vesicular membrane trafficking toward the axonal plasma membrane.
Synonyms: LLGL; DLG4; HUGL; HUGL1; Lgl1; Mgl1; HUGL-1
Tractability: Small molecule: a structure with a bound ligand is known. Antibody: its Gene Ontology location is reachable by antibodies, with medium confidence. PROTAC: ubiquitination databases record sites on it; its protein half-life has been measured.
Gene: Protein-coding gene on chromosome 17 (18,225,569 to 18,244,876, forward strand). Ensembl gene ENSG00000131899.
Subcellular location: Early endosome membrane; Golgi apparatus, trans-Golgi network membrane; Golgi apparatus membrane; Cell projection, axon; Cytoplasm, cytoskeleton
Gene Ontology:
Molecular function: protein binding; protein kinase binding; GTPase activator activity; myosin II binding; structural molecule activity
Biological process: cortical actin cytoskeleton organization; protein-containing complex assembly; axonogenesis; establishment of spindle orientation; establishment or maintenance of epithelial cell apical/basal polarity; Golgi to plasma membrane transport; regulation of establishment or maintenance of cell polarity; regulation of Notch signaling pathway
Cellular component: cortical actin cytoskeleton; cytoplasm; adherens junction; axon; cytoskeleton; early endosome membrane; Golgi cis cisterna; plasma membrane; trans-Golgi network membrane; Golgi apparatus; Golgi membrane
Genetic constraint (gnomAD): Loss-of-function variants: 56 observed, 104.67 expected, observed/expected ratio (o/e) 0.54, 90% interval 0.43 to 0.67. The upper end of that interval is the gene's LOEUF score, 0.67, which puts it in group 2 of 6, group 1 being the genes least tolerant of losing a copy. Missense variants: 1,189 observed, 1,444.8 expected, observed/expected ratio (o/e) 0.82, 90% interval 0.78 to 0.86. Synonymous variants: 654 observed, 606.52 expected, observed/expected ratio (o/e) 1.08, 90% interval 1.01 to 1.15.
Homologues: Orthologues: chimpanzee LLGL1 (99% identical), macaque LLGL1 (99% identical), dog LLGL1 (94% identical), guinea pig LLGL1 (90% identical), mouse Llgl1 (90% identical), pig LLGL1 (90% identical), rat Llgl1 (89% identical), rabbit LLGL1 (79% identical), tropical clawed frog llgl1 (71% identical), Drosophila melanogaster l(2)gl (38% identical), Caenorhabditis elegans lgl-1 (19% identical), zebrafish llgl1 (19% identical). Paralogues in human: LLGL2 (53% identical), STXBP5 (28% identical), STXBP5L (27% identical).
Diseases named in the same sentence as LLGL1 in open-access papers:
LLGL1 is named in the same sentence as 56 diseases in open-access papers, as found by Europe PMC text mining. Sharing a sentence is not in itself a finding about the gene and the disease. The quoted sentences say what the papers report.
malignant melanoma (7 papers, 2008 to 2024). "In 2005, loss of LLGL1 was associated with tumor-suppressive functions and was then linked with metastatic colorectal cancer, melanoma, endometrial cancer, hepatocellular cancer, pancreatic cancer, glioma, and lung cancer." (PMID 31058107, 2019). "Loss of LLGL1 has been associated with loss of cellular adhesion and dissemination of cells from colorectal cancer and malignant melanoma." (PMID 31058107, 2019). "LLGL1 encodes a cytoskeleton-associated protein involved in maintaining cell polarity; the loss of LLGL1 is associated with a loss of cellular adhesion, dissemination of cells, and distant metastases in several cancers including gastric cancer and malignant melanoma." (PMID 35892849, 2022). "Reduced expression or mutations in LLGL1 (also known as HUGL1), are associated with hepatocellular carcinoma, malignant melanoma and colorectal cancer." (PMID 38240353, 2024).
colorectal cancer (5 papers, 2011 to 2025). A primary or metastatic malignant neoplasm that affects the colon or rectum. "As highlighted in some studies, LLGL1 is deleted preferentially in CIN-type tumors, and the downregulation of this gene would seem to contribute to colorectal cancer progression." (PMID 22099067, 2011). "Matching our current observations in gastric cancer, LLGL1 expression did not impact on proliferation, cell cycle, or apoptosis in colorectal cancer." (PMID 31058107, 2019).
breast carcinoma (3 papers, 2016 to 2023). "Increased breast cancer metastases decrease patient survival, a correlation that we also observed with loss of Llgl1 expression." (PMID 27542214, 2016). "To investigate the differences caused by the loss of Llgl1 and the different populations that are observed, we evaluated the cells using breast cancer stem cell markers CD44, CD49f, and CD24." (PMID 27542214, 2016). "The eleven lines tested included triple negative and Her2 positive breast cancers of grade 2 or higher, and we observed that Llgl1 loss was associated with increased EGFR expression." (PMID 27542214, 2016). "We therefore analyzed a publicly available GEO data set (GSE3494) with 236 breast cancer patients for Llgl1 expression and long term survival." (PMID 27542214, 2016). "Llgl1 is down regulated in many cancers, including colorectal, endometrial, hepatocellular carcinoma, malignant melanomas, and breast cancer." (PMID 27542214, 2016). "Overall, these data indicate that Llgl1 expression may significantly affect tumor progression in breast cancer patients." (PMID 27542214, 2016). "In an attempt to address the role of Llgl1 in tumor progression, we transfected an Llgl1-GFP construct into breast cancer cell lines with little to no Llgl1 expression, including MDA-MB-453, MDA-MB-231, and T47D." (PMID 27542214, 2016).
esophageal cancer (3 papers, 2016 to 2022). A primary or metastatic malignant neoplasm involving the esophagus. "Lgl1 protein (encoded by LLGL1 gene) has been reported to exert tumor suppressor effects in esophageal cancer and colorectal cancer." (PMID 26934648, 2016). "LLGL1 has been implicated to play oncogenic roles in various types of malignancies, such as pancreatic ductal carcinoma, non-small-cell lung cancer, gliomas, and esophageal cancer, by regulating cell proliferation, invasion, apoptosis, and drug resistance." (PMID 35559038, 2022).
hepatocellular carcinoma (3 papers, 2016 to 2026). A malignant tumor that arises from hepatocytes. "It was reported that LLGL1 mRNA is frequently mutated by aberrant splicing, indicating that LLGL1 mutation may be involved in progression of hepatocellular cancer." (PMID 26934648, 2016).
gastric cancer (2 papers, 2019 to 2022). A primary or metastatic malignant neoplasm involving the stomach. "In summary, these data reveal that loss of LLGL1 protein staining is associated with the diffuse type gastric cancer." (PMID 31058107, 2019). "Loss of LLGL1 expression occurred in 65% of gastric cancers and significantly correlated with loss of E-cadherin expression (P=0.00009)." (PMID 31058107, 2019). "Loss of LLGL1 expression was significantly correlated with the diffuse type of gastric cancer (15/24; 63%) compared with the intestinal type (4/15; 27%; P=0.029)." (PMID 31058107, 2019). "Specifically, we were interested to know whether LLGL1 expression is lost in gastric cancer and if so whether loss of LLGL1 expression occurs in a larger context of cellular deadhesion." (PMID 31058107, 2019). "Loss of LLGL1 expression occurred in 65% of gastric carcinoma samples." (PMID 31058107, 2019). "We initiated this study to investigate the relevance of LLGL1 expression for gastric cancer development and progression." (PMID 31058107, 2019). "LLGL1 and E-cadherin transcription levels were evaluated in 56 gastric cancer patients and five gastric cancer cell lines." (PMID 31058107, 2019).
leukemia (2 papers, 2020 to 2023). A malignant (clonal) hematologic disorder, involving hematopoietic stem cells and characterized by the presence of primitive or atypical myeloid or lymphoid cells in the bone marrow and the blood. "Re-expression of HoxA9 in Llgl1-deficient leukemic cells resulted in a complete phenotypic rescue and resulted in lethal leukemia with 100% penetrance (median survival 56 days)." (PMID 37587260, 2023). "Following induction of Mx1-Cre recombinase by repeated pIpC injections at 4 weeks of age, FLT3ITD/ITD; Llgl1+/+ animals developed rapid onset of leukemia with a median survival of 37 days." (PMID 37587260, 2023). "Inactivation of LLGL1 results in loss of stemness-associated gene-expression including HoxA-genes and induces a GMP-like phenotype in the leukemia stem cell compartment." (PMID 37587260, 2023). "As expected, injection of equal numbers (1.5 × 105 GFP+) of empty-vector transduced FLT3ITD/ITD; Llgl1+/+; Mx+ cells induced leukemia in 50% of recipient animals (median survival: 63 days)." (PMID 37587260, 2023). "Llgl1 deletion by itself did not cause leukemia, however, its expression was correlated with decreased survival in AML." (PMID 37587260, 2023). "As genetic deletion of Llgl1 may result in disturbed cell adhesion and division, we sought to validate its function in a model system that allows assessment of functional consequences following conditional Llgl1 deletion in adult hematopoietic cells and also in established leukemia." (PMID 37587260, 2023). "Histopathologic analysis of hematopoietic organs showed decreased leukemia infiltration in FLT3ITD/ITD; Llgl1−/− animals and a rescued organ architecture." (PMID 37587260, 2023).
metastatic melanoma (2 papers, 2022 to 2024). A melanoma that has spread from its primary site to another anatomic site. "The expression of the LLGL1 gene was found to be upregulated by ALKBH5 in xenograft tumours, while ALKBH5 and MIEF2 were upregulated together in the T regulatory cells of metastatic melanoma." (PMID 39596561, 2024).
acute leukemia (1 paper, 2023). A clonal (malignant) hematopoietic disorder with an acute onset, affecting the bone marrow and the peripheral blood. "Taken together, cell-type specific functions of Scribble complex member Llgl1 could be confirmed in acute leukemia, which may suggest a possible disease specific modulation of cell polarity complexes." (PMID 37587260, 2023).
acute myeloid leukemia (1 paper, 2023). Acute myeloid leukemia (AML) is a group of neoplasms arising from precursor cells committed to the myeloid cell-line differentiation. "We address the issue of context dependent effects of Llgl1 inactivation in models of acute myeloid leukemia and provide evidence that Llgl1 is functionally required for maintenance of an undifferentiated state and proliferative capacity of AML." (PMID 37587260, 2023). "In order to confirm our findings in a second oncogenic model of acute myeloid leukemia, we crossed FLT3-ITD knock-in mice with transgenic animals expressing the interferon inducible Mx1-Cre-recombinase and the conditional Llgl1 knockout." (PMID 37587260, 2023).
Cirrhosis (1 paper, 2012). A chronic disorder of the liver in which liver tissue becomes scarred and is partially replaced by regenerative nodules and fibrotic tissue resulting in loss of liver function. "The cytoskeleton (COMMD5, KRTAP19-5, LLGL1 and SNX17) related genes were down-regulated in cirrhosis (F4)." (PMID 22397681, 2012).
diffuse gastric cancer (1 paper, 2019). "Thus, loss of LLGL1 might contribute to the mechanical dissemination of cancer cells as seen in diffuse gastric cancer with consecutive peritoneal carcinomatosis." (PMID 31058107, 2019).
endometrial cancer (1 paper, 2019). Primary or metastatic malignant neoplasm involving the endometrium (mucous membrane that lines the endometrial cavity). "In addition, Tsuruga and colleagues described loss of LLGL1 expression in endometrial cancer and reported a correlation with metastatic disease." (PMID 31058107, 2019).
glioblastoma (1 paper, 2014). The most malignant astrocytic tumor (WHO grade IV). "Recently we have shown that a human homolog of Lgl, Lgl1 (LLGL1), is constitutively phosphorylated and inactivated in glioblastoma cells; this occurs as a downstream consequence of PTEN loss, one of the most frequent genetic events in glioblastoma." (PMID 25426552, 2014).
lymphoid neoplasm (1 paper, 2023). A neoplasm composed of a lymphocytic cell population which is usually malignant (clonal) by molecular genetic and/or immunophenotypic analysis. "Likewise, loss of Llgl1 had not altered the course of murine lymphoid neoplasms induced by constitutive Notch, c-Myc or Jak2 expression." (PMID 37587260, 2023).
myeloid leukemia (1 paper, 2023). A clonal proliferation of myeloid cells and their precursors in the bone marrow, peripheral blood, and spleen. "These conditional Llgl1 knockout animals were intercrossed with Mx1-Cre+ animals and a conventional (straight) MLL-AF9 knock-in model that develops myeloid leukemia with a median latency of 5-6 months." (PMID 37587260, 2023).
tumor (32 papers, 2011 to 2026). "In addition, LLGL1 could rescue its mutated respective Drosophila homologue, demonstrating a conserved tumor suppressor function." (PMID 31058107, 2019). "Our data shows that Llgl1 is a necessary regulator in the prevention of metaplasia and that its loss results in multiple aberrant characteristics, all of which can decrease patient survival, warranting further exploration of Llgl1 as a tumor suppressor and potential therapeutic target." (PMID 27542214, 2016). "LLGL scribble cell polarity complex component 1 (LLGL1) is an evolutionarily conserved polarity protein with well-established tumor-suppressive roles in multiple epithelial malignancies." (PMID 41977148, 2026). "Collectively, these findings position LLGL1 loss as a central factor associated with altered MAPK signaling, EMT marker remodeling, and tumor-promoting cellular phenotypes in HCC." (PMID 41977148, 2026). "SCRIBBLE is both a positive effector in PCP and a major regulator of apical–basal polarity as part of a complex with DLG (Disc Large) and LLGL1 (Lethal Giant Larvae homologue), which has tumor suppressing functions." (PMID 36675340, 2023). "miR-665 can promote the biological behavior of SCLC cells by inhibiting the expression of target gene LLGL1, and miR-665 play a role in tumor-promoting genes in SCLC." (PMID 32222154, 2020). "According to our data, abolishing GIRDIN function in tumor cells with decreased levels of the human Lgl protein LLGL1, as reported in many cancers, could also support the progression of the disease by altering the polarity phenotype." (PMID 32196494, 2020). "In a nude mouse xenograft model of SCLC, inhibition of miR-665 expression could up-regulate LLGL1 protein expression and inhibit tumor growth, while up-regulation of miR-665 expression could produce opposite results." (PMID 32222154, 2020). "Analysis of patient survival data indicates that these changes may be important indicators of Llgl1's tumor suppressor capability." (PMID 27542214, 2016). "In contrast, tumor suppressor function of Llgl1 was not conserved in murine models of lymphoid (B- and T-cell) leukemia." (PMID 37587260, 2023). "On the other hand, the tumor suppressor function of Llgl1 was not conserved in murine models of lymphoid (B- and T-cell) leukemia suggesting that Llgl1 may act in a highly cell context specific manner." (PMID 37587260, 2023).
cancer (19 papers, 2010 to 2025). A tumor composed of atypical neoplastic, often pleomorphic cells that invade other tissues. "Llgl1's role as a polarity regulator in the Scribble complex is important, and as we have shown, its loss results in an increase of cancer stem-cell like qualities, migration, and transplant survival in an EGF-dependent manner." (PMID 27542214, 2016). "Further studies revealed that loss of LLGL1 expression is lost in various cancers." (PMID 31058107, 2019). "As occurs in Drosophila, the mislocalization or dysfunction of LLGL1 and/or LLGL2 in cancer is also associated with altered aPKC localization or activity." (PMID 38240353, 2024). "A total of 10 genes that were disrupted or within breakpoint‐associated TAD structures were classified as known (FHIT, FLCN, NCOA4, and RET) or candidate cancer genes (LLGL1, LRIG1, LYRM9, RASGEF1A, ST3GAL6, and TMEM199)." (PMID 31943436, 2020). "We previously showed that the human ortholog of Drosophila lgl, namely LLGL1 or HUGL-1, is functionally conserved, and our and other studies associated its transcriptional deregulation and/or protein delocalization with several types of cancers." (PMID 36704198, 2022). "Interestingly, expression of LLGL1 significantly enhanced the adhesion of cancer cells to plastic, laminin, and fibronectin." (PMID 31058107, 2019). "Interestingly, several of these small and large altered regions contain cancer-associated genes known to be involved in CRC and/or the metastatic process: i.e. the TPD52, FABP5, MAP2K4, LLGL1, FBLN1 and TYMP genes." (PMID 21060790, 2010). "Moreover, LLGL1 has already been proposed as a prognostic marker of various cancers." (PMID 35559038, 2022). "Mislocalization of LLGL1 and/or LLGL2 is also observed in other human cancers, including lung adenocarcinoma and ovarian cancer." (PMID 38240353, 2024). "Analysis demonstrated two known cancer genes (NCOA4 and RET) and a further five candidate cancer genes (LLGL1, LRIG1, LYRM9, ST3GAL6, and TMEM199) were within breakpoint‐containing TADs." (PMID 31943436, 2020). "LLGL1 was expressed in gastric AGS, NCI-N87, OE33 and MKN cancer cell lines." (PMID 31058107, 2019).
LLGL1 also shares sentences with these, for which no sentence is quoted: colitis (6 papers); infection (6); lung carcinoma (3); ovarian carcinoma (3); colon cancers (2); glioma (2); helminth infection (2); lung squamous cell carcinoma (2); non-small cell lung carcinoma (2); Obesity (2); adenocarcinoma (1); autoimmune disease (1); bone tumors (1); brain tumours (1); cyst (1); cysticercosis (1); dermatitis (1); experimental autoimmune encephalomyelitis (1); gastric adenocarcinoma (1); in situ carcinoma (1); iron deficiency (1); lung adenocarcinoma (1); lymph node metastasis (1); lymphoma (1); mastocytoma (1); metastatic cancer (1); metastatic disease (1); oral diseases (1); pancreatic ductal carcinoma (1); Parkinson disease (1).
A further 8 diseases each share a sentence with LLGL1 in 1 paper.